ICAM1 (intercellular adhesion molecule 1)
Diseases named in the same sentence as ICAM1 in open-access papers (continued):
Sharing a sentence is not in itself a finding about the gene and the disease.
sinus (1 paper, 2012). "ApoE−/− mice treated with ARE had significantly smaller aortic sinus lesions, lower numbers of macrophages in the aortic wall, and decreased expression levels of adhesion molecules (VCAM-1 and ICAM-1) in the vessel wall compared with control mice." (PMID 22536886, 2012).
skin infection (1 paper, 2022). An inflammatory process affecting the skin, caused by bacteria, viruses, parasites, or fungi. "One day after secondary skin infection (day 29), the subcapsular sinus showed an increase in CD54-expressing dendritic, endothelial, and ICAM-1+ cells compared with days 8 and 28 after the initial infection." (PMID 35625758, 2022). "After secondary skin infection, a significant increase in the area positive for CD54-expressing dendritic, endothelial, and ICAM-1+ cells was observed compared with observations made on days 8 and 28 after the initial infection." (PMID 35625758, 2022).
small cell lung carcinoma (1 paper, 2019). Small cell lung cancer (SCLC) is a highly aggressive malignant neoplasm, accounting for 10-15% of lung cancer cases, characterized byrapid growth, and early metastasis. "In addition, a trend toward a higher risk of death and high ICAM-1 levels (p = 0.06) was revealed by correlative studies of a phase II trial assessing the efficacy and safety of a bevacizumab and cisplatin, etoposide combination in 63 patients with extensive stage small-cell lung cancer." (PMID 31752122, 2019).
sympathetic ophthalmia (1 paper, 2022). Sympathetic ophthalmia (SO) is a bilateral granulomatous anterior uveitis usually occurring within the three months following trauma or a surgical procedure involving one eye. "For example, in patients with sympathetic ophthalmia, the expression of VLA-4, VLA-5, VCAM-1, ICAM-1, and CD44 in the peripheral blood was significantly increased in acute inflammation compared to either the disease resolution phase or normal eyes." (PMID 35008929, 2022).
Thiamine deficiency (1 paper, 2025). Thiamine deficiency is a condition that occurs due to not enough thiamine (vitamin B1). "Findings indicate a range of biomarkers—such as heme oxygenase (HO-1), superoxide dismutase (SOD), intercellular adhesion molecule 1 (ICAM-1), nitric oxide endothelial synthase (eNOS), nitric oxide inducible synthase (iNOS), ferritin, and malondialdehyde—increase in cases of thiamine deficiency." (PMID 40243711, 2025).
thoracic cancer (1 paper, 2026). A primary or metastatic malignant neoplasm affecting the tissues of the thorax. "Coxsackievirus A11 demonstrates exceptional selectivity for thoracic cancers through ICAM-1-dependent receptor tropism and potent immunogenic cell death induction." (PMID 42043250, 2026).
thymoma (1 paper, 2023). A neoplasm arising from the epithelial cells of the thymus. "Based on the TCGA dataset, we also showed that IFN-γ, ICAM1, and TNF expression were decreased in thymoma; however, CCL2 expression was considerably increased." (PMID 37644514, 2023).
thyroid nodule (1 paper, 2023). A small circumscribed mass in the THYROID GLAND that can be of neoplastic growth or non-neoplastic abnormality. "On the other hand, we demonstrated that mRNA expression of SELL and ICAM1 and protein expression of L-selectin and LFA-1 can help in the histological characterization of thyroid nodules with a follicular pattern." (PMID 36906717, 2023).
toxoplasmosis (1 paper, 2022). A parasitic disease contracted by the ingestion or fetal transmission of toxoplasma gondii. "The data suggest an implication of leukocyte ICAM-1 in the pathogenesis of toxoplasmosis." (PMID 35990682, 2022).
Trichinella spiralis infection (1 paper, 2018). "Trichinella spiralis infection markedly enhanced the levels of proinflammatory cytokines (TNF-α, IL-6, IL-17, and ICAM-1, P < 0.01) but remarkably reduced the level of anti-inflammatory cytokine (IL-10) in colon, compared with control group (P < 0.01)." (PMID 29662452, 2018).
tuberculous pleuritis (1 paper, 1996). "We analysed levels of soluble vascular cell adhesion molecule-1 (s.VCAM-1), soluble intercellular adhesion molecule-1 (s.ICAM-1), and soluble E-selectin (sE-selectin) in serum and pleural fluid from patients with tuberculous pleuritis, by sandwich ELISA." (PMID 18475740, 1996).
urolithiasis (1 paper, 2022). Stone(s) within the urinary tract. "Our previous studies showed that the serum levels of VCAM-1 and ICAM-1 were elevated in patients with urolithiasis." (PMID 35328466, 2022).
uveal tumor (1 paper, 2008). "ETS-2 and ERM (ets variant 5) also significantly increase transcription of the gene encoding intercellular adhesion molecule-1 (ICAM-1), which has a major role in uveal tumor growth." (PMID 18958307, 2008).
venous ulceration (1 paper, 2023). "In clinical trials, diosmin decreased the expression of monocytes or neutrophils, and the endothelial activation markers of the intercellular adhesion molecule 1 (ICAM-1) and the vascular cell adhesion molecule 1 (VCAM-1) on human leukocytes in patients with venous ulceration." (PMID 37371797, 2023).
West-Nile encephalitis (1 paper, 2024). "ICAM-1 knockout mice exhibit decreased lethality from West Nile encephalitis due to reduced viral load, leukocyte infiltration, and neuronal damage." (PMID 38479396, 2024).
α+thalassemia (1 paper, 2014). "Patterns of pRBC binding to ICAM1 were similar to those seen for CD36, with homozygous α+thalassemia being associated with significantly lower pRBC binding (1891.9; 1320.5–2565.7) in comparison to normal pRBCs (2858.2; 2057.1–3790.8; P = 0.007)." (PMID 25893206, 2014). "We investigated the effect of co-inherited HbAS and α+thalassemia on cytoadhesion of pRBCs infected with parasites of the ItG strain (which binds to both CD36 and ICAM1) in a total of 99 RBC samples of various Hb and α+thalassemia genotype combinations." (PMID 25893206, 2014).
tumor (1,384 papers, 1994 to 2026). "This elevated ICAM-1 expression was associated with the formation of stable contacts with tumor cells, leading to enhanced NK cell-mediated cytotoxicity." (PMID 39911389, 2025). "Particularly noteworthy is the robust positive correlation between TIGD1 and HMGB1 expression across nearly all tumor types, along with significant associations with ICAM1, CCL5, and TNFRSF18 in the majority of cancers." (PMID 40565566, 2025). "Elevated levels of VCAM-1 and ICAM-1, particularly in tumor tissue, were strongly associated with recurrence, underscoring their potential as biomarkers and therapeutic targets." (PMID 40652770, 2025). "Elevated VCAM-1 and ICAM-1 levels in tumor tissue were strongly associated with increased cancer recurrence risk, suggesting their involvement in metastasis and immune evasion." (PMID 40652770, 2025). "Because ICAM-1 is produced by tumor cells, there is a notable association between serum ICAM-1 levels and its expression in tumor tissues." (PMID 41179937, 2025). "ICAM1 is a key player in neutrophil adhesion and is associated with neutrophil anti-tumor phenotype." (PMID 40867260, 2025). "Tumor-associated vasculature expresses adhesion molecules, such as ICAM-1 and VCAM-1, to facilitate lymphocyte transmigration." (PMID 40475782, 2025). "Immune modulatory molecules, such as CCL2 and CCL5, which recruit tumor-associated macrophages, and adhesion molecules ICAM1 and VCAM1, which facilitate immune cell trafficking, were also included." (PMID 40652770, 2025). "Tumor vessels in hypoxic environments are often leaky, disorganized, and deficient in adhesion molecules such as ICAM-1 and VCAM-1, which are necessary for T cell extravasation." (PMID 41048631, 2025). "As a ligand for the integrin LFA-1 (lymphocyte function-associated antigen-1), ICAM-1, a member of the immunoglobulin superfamily, allows tumor cells, especially melanocytes, to interact with circulating lymphocytes." (PMID 41313526, 2025). "The tumor-associated EC altered glycosylation of surface adhesion molecules including ICAM-1, VCAM-1, and PECAM, and glycan-binding proteins (lectins) also promote tumor progression and metastasis by modifying the adhesive properties of ECs." (PMID 38426109, 2024). "Eosinophils bind ICAM-1 in the surface of tumor cells through leukocyte function-associated antigen 1 (LFA-1) (CD11a/CD18 integrin) and ITGAM (CD11b/CD18 integrin)." (PMID 38892286, 2024). "Data were aggregated from several prominent databases, including HPA, cBioPortal, GTEx, CCLE, and TCGA, to ascertain the expression levels of ICAM1 in relation to tumor mutation burden and MSI in 11 different malignancies." (PMID 39767561, 2024). "The vasoconstrictive peptide endothelin 1 (ET1) is associated with ICAM-1 expression and the decreased presence of tumor-infiltrating leukocytes." (PMID 38576482, 2024). "In context of this conclusion, and as a therapeutic approach, tumor cells were intracranially injected into ICAM-1 deficient mice leading to a longer survival with a lower overall tumor volume comparet to the wild type." (PMID 39050471, 2024). "Hypoxia within the TME seems to play a pivotal role in impairing the expression of both VCAM-1 and of diverse adhesion molecules such as E-selectin, P-selectin, and ICAM-1 on the surface of tumor cells or tumor-associated cells." (PMID 39596815, 2024). "While ICAM1 has been associated with tumour-induced bone metastasis, its potential involvement in the pathogenesis of SONFH warrants further exploration." (PMID 39069636, 2024). "Regarding drug resistance, this study discovered that the group exhibiting high ICAM-1 expression can be susceptible to eight medications, such as sorafenib, which are linked to angiogenesis, apoptosis, and tumor cell proliferation." (PMID 38799250, 2024). "ICAM1 is an immunoglobulin implicated in metastasis via homophilic interactions that enhance circulating tumor cell cluster formation and tumor-endothelial cell adhesion and migration." (PMID 39409003, 2024).
tumor (continued). "Elevated ICAM1 expression has been consistently associated with a poor prognosis across diverse tumor types." (PMID 38907234, 2024). "The analysis indicated a significant association between ICAM1 expression levels and tumor mutation burden in 11 malignancies." (PMID 39767561, 2024). "LN3 T-ALL cells were co-cultured with tumor-associated myeloid cells in the presence of anti-ICAM-1 and/or anti-VCAM-1 blocking antibodies." (PMID 37805579, 2023). "Previous evidence has presented that hyperactivation of the NF-κB signaling pathway causes the expression of intercellular adhesion molecule 1 (ICAM1) and increases cell-endothelial cell adhesion and metastasis, all of which are the hallmarks of a tumor." (PMID 36820951, 2023). "Paradoxically, ICAM1 on tumor cells is previously associated with cancer metastasis and immune evasion." (PMID 36871040, 2023). "TAMs were localized in the center of spheroids and secreted EGF, which upregulated the αMβ2 integrin on TAMs and ICAM-1 on tumor cells to promote association between tumor cells and TAMs." (PMID 37508575, 2023). "The possible mechanism underlying ICAM1-dependent-T-cell homing on tumor is that the high secreted ICAM1 gradient from the cancer cell source attracts cytotoxic T cells to move toward tumor cells." (PMID 36871040, 2023). "Many studies have demonstrated that IL-6 and TNF-a enhance tumor cell adhesion and that this is associated with an increased expression of ICAM-1 and VCAM-1 by mesothelial cells." (PMID 38068319, 2023). "While tumor-associated macrophages, cDC2s and monocytes all express ICAM-1, only tumor-associated macrophages express high levels of VCAM-1." (PMID 37805579, 2023). "A loss of function study targeting ICAM‐1 revealed that it is a crucial molecule that determines the anti‐tumor efficacy of anti‐PD‐1 therapy." (PMID 37097643, 2023). "We examined ICAM1 expression levels’ association with stromal cells, tumor purity, and immunological scores." (PMID 37671167, 2023). "Overexpression of Icam1 sensitized Lkb1-deficient tumors to anti-PD-1 immunotherapy as better tumor control." (PMID 36871040, 2023). "Histopathological staining (HE, TUNEL, Ki-67, VCAM-1, and ICAM-1) was used to determine the mechanism of tumor suppression caused by PDT with different light fields." (PMID 36591528, 2022). "In this regard, systemic thermal therapy has been shown to be associated with IL-6 production, leading to ICAM-1 expression by the tumor blood vessels and, thus, favoring the entry of T cells into the tumor site." (PMID 35681548, 2022). "An immunofluorescent analysis showed that TGF-β1 and IGF-1 upregulate the expression of other adhesion-associated molecules, such as ICAM-1 and vimentin, on the surface of ascites-treated tumor cells and peritoneal cells." (PMID 35682890, 2022). "This T cell enrichment in tumor cell regions was associated with a marked increase in ICAM-1 expression on tumor cells and was inhibited by a blocking monoclonal IFNγ antibody." (PMID 36189315, 2022). "VCAM-1 and ICAM-1 were highly expressed in sparse LEDs-PDT treated tumor tissues and were associated tumor angiogenesis, which in turn lead to poor tumor suppression." (PMID 36591528, 2022). "Further, CpG-ODN (oligodeoxynucleotides, ODN) vaccination caused up-regulation of ICAM-1 on tumor-associated blood vessel endothelia leading to tumor-infiltration of T cells and tumor suppression in mouse model of pancreatic carcinoma." (PMID 36505809, 2022). "Several studies associate ICAM-1 expression with a more aggressive tumor phenotype and higher metastatic potential." (PMID 34299272, 2021). "In that sense, a clinical study analyzing patients with CLD from different etiologies reported the association of soluble ICAM-1 with an advanced tumor stage in HCC." (PMID 35008212, 2021).
tumor (continued). "Our results demonstrated that CX3CL1/ICAM-1 signaling, which underlies tumor cell-endothelium interactions, constituted a vicious feedback cycle between circulating NSCLC cells and the bone microenvironment to promote NSCLC spinal metastasis." (PMID 33754027, 2021). "ICAM-1 has been reported to have anti-tumor effects, whereas PD-L1 is associated with T-cell inhibition with pro-tumor effects." (PMID 33653826, 2021). "We found that the upregulation of ICAM-1 made the tumor cells more susceptible to NK cells, suggesting that ICAM-1 is the functional target of miR-6852-3p in HCC." (PMID 33462208, 2021). "In keeping with the phenotypic loss of HEVs in tumor LNs, the expression levels of Glycam1, Chst4, Icam1, and Ccl21a were progressively reduced in HEC1 to HEC3, similar to the reduction of gene expression of PNAd producing glycan-generating enzymes." (PMID 34706240, 2021). "VEGF also restricts the migration of Teff cells into the tumor microenvironment by downregulating the expression of adhesion molecules including ICAM-1 and VCAM-1 on tumor-associated endothelial cells." (PMID 33746989, 2021). "The interaction between T cell-expressed lymphocyte function-associated antigen 1 (LFA1) and intercellular adhesion molecule 1 (ICAM1) on the intravascular endothelium activates T cell infiltration into the tumor tissue." (PMID 34071550, 2021). "ICAM-1 deficiency increases M2 macrophage polarization and suppress tumor metastasis, but others reported that downregulation of ICAM-1 in RAW264.7 macrophages resulted in inflammatory M1 polarization." (PMID 32121422, 2020). "The vasoconstrictive peptide Endothelin 1 (ET1), known for its direct effect on angiogenesis via VEGF and HIF1, is also associated with ICAM1 expression and the decreased presence of tumor infiltrating leukocytes (TIL)." (PMID 32974337, 2020). "In ovarian cancer, immune cells such as M2 macrophage-like TAMs secrete EGF, which upregulates αMβ2 integrin on TAMs and ICAM-1 on tumor cells to promote association between tumor cells and TAMs." (PMID 32780245, 2020). "Rather, host ICAM-1 expression affected the priming of adoptively transferred tumor-antigen-specific CD8+ T cells leading to delayed tumor rejection in ICAM-1 deficient mice." (PMID 31231358, 2019). "In tumor-associated fibroblasts, the cellular expression of ICAM-1 is increased compared to normal tissue-associated fibroblasts, indicating a tumor microenvironment–dependent upregulation of its expression." (PMID 30470940, 2019). "Genomic DNA was isolated from whole blood for the analysis of VEGF-A (rs2010963, 1570360, rs699947), ICAM-1 (rs5498, rs1799969) SNPs and from tumor tissue for the detection of genomic variants in KRAS, NRAS, BRAF genes." (PMID 31752122, 2019). "Soluble ICAM-1 is an inflammation-associated marker and is therefore increased in patients with an inflammatory tumor microenvironment." (PMID 30470940, 2019). "Several studies have investigated the relationship between ICAM-1 gene polymorphisms and tumour susceptibility, but results showed inconsistency." (PMID 31244280, 2019). "Decreases the ICAM-1 expression and restricts the association of cytotoxic T lymphocyte cells to tumor cells." (PMID 32038627, 2019). "In the current study, we found that advanced tumor stage and chemotherapy tolerance were associated with high ICAM-1 expression in HGSOC and that ICAM-1 overexpression is associated with an increased risk of death for HGSOC." (PMID 31312656, 2019). "ITGAL, the counterreceptor-ligand of ICAM1, was expressed in immune cells surrounding the tumor cells, both in the periphery and central tumor, as well as in the tumor-associated TLS." (PMID 30082828, 2018). "The tumor was capable of modifying the SN environment to be tolerogenic by forming chronic inflammation, causing the synergistic effects of ICAM-1 and TGFβ2 signal, together with exhaustion and Tc2 skewed environment, to suppress CD8+ T cells cytotoxicity." (PMID 29966014, 2018).